PRPF38B (pre-mRNA processing factor 38B)
Description:
May be required for pre-mRNA splicing.
Synonyms: FLJ10330; NET1
Tractability: PROTAC: ubiquitination databases record sites on it; its protein half-life has been measured.
Gene: Protein-coding gene on chromosome 1 (108,692,310 to 108,702,928, forward strand). Ensembl gene ENSG00000134186.
Subcellular location: Nucleus
Gene Ontology:
Molecular function: RNA binding
Cellular component: precatalytic spliceosome; nucleus
Genetic constraint (gnomAD): Loss-of-function variants: 18 observed, 64.97 expected, observed/expected ratio (o/e) 0.28, 90% interval 0.19 to 0.41. The upper end of that interval is the gene's LOEUF score, 0.41, which puts it in group 1 of 6, group 1 being the genes least tolerant of losing a copy. Missense variants: 540 observed, 716.63 expected, observed/expected ratio (o/e) 0.75, 90% interval 0.7 to 0.81. Synonymous variants: 246 observed, 248.66 expected, observed/expected ratio (o/e) 0.99, 90% interval 0.89 to 1.1.
Homologues: Orthologues: macaque PRPF38B (99% identical), rabbit PRPF38B (79% identical).
Diseases named in the same sentence as PRPF38B in open-access papers:
PRPF38B is named in the same sentence as 16 diseases in open-access papers, as found by Europe PMC text mining. Sharing a sentence is not in itself a finding about the gene and the disease. The quoted sentences say what the papers report.
breast carcinoma (2 papers, 2017 to 2025). "After 2006, patients with ER-negative/HER2-positive breast cancer were treated with trastuzumab and, in these patients, membranous expression of PRPF38B in the primary cancer was significantly associated with better disease-free survival (DFS) at the 5 year follow-up." (PMID 29348822, 2017). "This study demonstrates that the expression of PRPF38B is an independent prognostic marker in breast cancer." (PMID 29348822, 2017). "The identification of membranous PRPF38B expression in breast cancer affords the opportunity to develop an antibody targeting strategy for therapeutic intervention." (PMID 29348822, 2017). "This study therefore reveals and highlights the potential importance of membranous PRPF38B expression as a parameter for predicting therapeutic response to trastuzumab therapy in patients with ER-negative/HER2-positive breast cancer." (PMID 29348822, 2017). "Previous research has suggested that the PRPF38B gene may function as a prognostic biomarker for breast cancer patients with HER2 overexpression who are receiving trastuzumab therapy." (PMID 40711007, 2025). "Our subsequent detection of PRPF38B in a SEREX screen of sera from patients with breast cancer and the demonstration that it is over-expressed in breast cancer tissue led us to evaluate PRPF38B expression as a prognostic and therapeutic outcome predictor in a large series of breast cancers." (PMID 29348822, 2017). "Furthermore, membranous expression of PRPF38B was significantly associated with a poor prognosis at the 5 year follow-up in patients with ER-negative/HER2-positive breast cancer who were treated prior to 2006 and did not receive trastuzumab therapy." (PMID 29348822, 2017). "Our findings suggest that determining the localization of PRPF38B expression in patients with ER-negative and ER-negative/HER2-positive breast cancer has the potential to stratify these patients for therapy." (PMID 29348822, 2017). "In the wider context, the significance of membranous PRPF38B as a biomarker for response to trastuzumab therapy may not be solely restricted to breast cancer." (PMID 29348822, 2017).
angina pectoris (1 paper, 2024). The symptom of paroxysmal pain consequent to MYOCARDIAL ISCHEMIA usually of distinctive character, location and radiation. "Based on information from FUMA and GeneCards, we found that several cluster-specific genes have been previously associated with individual psychiatric or somatic traits in the disease cluster (e.g., PRPF38B for angina pectoris and myocardial infarction)." (PMID 38332132, 2024).
colon cancer (1 paper, 2012). "MRE11A and PRPF38B showed more than 2.5-fold expression in all colon cancer specimens." (PMID 23151147, 2012).
invasive breast carcinoma (1 paper, 2017). A carcinoma that infiltrates the breast parenchyma. "Out of 1650 cases of early stage invasive breast cancer, 1388 were suitable for the scoring of PRPF38B expression." (PMID 29348822, 2017). "The current study investigated the clinicopathological significance of the expression of PRPF38B in a consecutive series of normal breast tissue (n = 40), primary invasive breast carcinomas (n = 1650) and ER-negative disease (n = 627)." (PMID 29348822, 2017). "The prevalence, clinicopathological and prognostic significance of PRPF38B expression in a consecutive series of 1650 patients with primary invasive breast carcinoma were examined using immunohistochemistry." (PMID 29348822, 2017).
ovarian carcinoma (1 paper, 2021). A malignant neoplasm originating from the surface ovarian epithelium. "Our splicing regulation network analysis showed some splicing factors might be correlated with prognosis-related AS events, including SPEN, SF3B5, RNPC3, LUC7L3, SRSF11 and PRPF38B, suggesting that these splicing factors could play crucial roles in ovarian cancer development." (PMID 34001978, 2021).
tumor (2 papers, 2017 to 2021). "In contrast, membranous PRPF38B staining was associated with aggressive phenotypes including ER-negative, PR-negative, HER-overexpression, high pleomorphism and high tumour grade." (PMID 29348822, 2017). "However, it could be that membranous PRPF38B expression is a surrogate biomarker for highly proliferative tumours." (PMID 29348822, 2017). "In addition, survival-related AS events might be involved in tumor-related pathways including base excision repair and pyrimidine metabolism pathways, and some splicing factors might be correlated with prognosis-related AS events, including SPEN, SF3B5, RNPC3, LUC7L3, SRSF11 and PRPF38B." (PMID 34001978, 2021).
PRPF38B also shares sentences with these, for which no sentence is quoted: cancer (2 papers); benign prostatic hyperplasia (1); gastric cancer (1); invasive ductal carcinoma (1); kidney cancer (1); lymph node metastases (1); myocardial infarction (1); neuroblastoma (1); prostate carcinoma (1); thalassemia (1).